DNAJC18 (DnaJ heat shock protein family (Hsp40) member C18)
Description:
(Microbial infection) In case of infection by polyomavirus, involved in the virus endoplasmic reticulum membrane penetration and infection. Regulates the recruitment of DNAJB12:DNAJB14 into SV40-induced foci and all cooperate to guide SV40 across the endoplasmic reticulum membrane. The foci represent the site from which SV40 penetrates into the cytosol.
Synonyms: MGC29463
Tractability: Antibody: UniProt predicts a signal peptide or a membrane-spanning region. PROTAC: ubiquitination databases record sites on it.
Gene: Protein-coding gene on chromosome 5 (139,408,588 to 139,444,491, reverse strand). Ensembl gene ENSG00000170464.
Subcellular location: Endoplasmic reticulum membrane
Subcellular location (Human Protein Atlas): Cell Junctions; Cytosol
Gene Ontology:
Molecular function: Hsp70 protein binding
Biological process: cellular response to misfolded protein; protein folding
Cellular component: endoplasmic reticulum membrane; endoplasmic reticulum
Genetic constraint (gnomAD): Loss-of-function variants: 32 observed, 42.97 expected, observed/expected ratio (o/e) 0.74, 90% interval 0.56 to 1. The upper end of that interval is the gene's LOEUF score, 1, which puts it in group 4 of 6, group 1 being the genes least tolerant of losing a copy. Missense variants: 323 observed, 429 expected, observed/expected ratio (o/e) 0.75, 90% interval 0.69 to 0.83. Synonymous variants: 128 observed, 155.02 expected, observed/expected ratio (o/e) 0.83, 90% interval 0.71 to 0.96.
Homologues: Orthologues: chimpanzee DNAJC18 (99% identical), macaque DNAJC18 (99% identical), pig DNAJC18 (96% identical), rabbit DNAJC18 (94% identical), guinea pig DNAJC18 (93% identical), mouse Dnajc18 (90% identical), rat Dnajc18 (90% identical), dog DNAJC18 (83% identical), Caenorhabditis elegans dnj-14 (16% identical), Drosophila melanogaster Csp (15% identical), Drosophila melanogaster CG10565 (14% identical), Caenorhabditis elegans dnj-8 (13% identical), and 8 more. Paralogues in human: DNAJC21 (23% identical), DNAJC13 (21% identical), DNAJC5B (20% identical), DNAJC16 (18% identical), DNAJC10 (18% identical), DNAJC5 (17% identical), DNAJC2 (16% identical), DNAJC14 (15% identical), DNAJC11 (15% identical), DNAJC1 (14% identical), DNAJC25 (12% identical), DNAJC5G (12% identical), and 8 more.
Diseases named in the same sentence as DNAJC18 in open-access papers:
DNAJC18 is named in the same sentence as 10 diseases in open-access papers, as found by Europe PMC text mining. Sharing a sentence is not in itself a finding about the gene and the disease. The quoted sentences say what the papers report.
Alzheimer disease (1 paper, 2025). A progressive, neurodegenerative disease characterized by loss of function and death of nerve cells in several areas of the brain leading to loss of cognitive function such as memory and language. "Although absent from the Open Targets Alzheimer’s disease gene list, TBEP prioritized DNAJC18 based on its strong tissue specificity and functional relevance in tau pathology." (PMID 41234055, 2025).
bladder carcinoma (1 paper, 2018). "Little is known about the protein coded by DNAJC18, but a polymorphic variant has been associated with aggressive bladder carcinoma." (PMID 29954368, 2018).
breast carcinoma (1 paper, 2018). "Another interesting observation from the present study is that several HSPs were downregulated in all breast cancer subtypes: DNAJB4, DNAJC18, HSPA12A, HSPA12B, HSPB2, HSPB6, and HSPB7." (PMID 29954368, 2018).
cardiomyopathy (1 paper, 2024). A disease of the heart muscle or myocardium proper. "In addition, Dnajc18 has recently been identified to be involved in congenital and structural heart disorders and cardiomyopathy in both humans and mice." (PMID 39156629, 2024).
COVID-19 (1 paper, 2025). A disease caused by infection with severe acute respiratory syndrome coronavirus 2. "Our analysis of the cis-eQTL effects of the SNP rs1042665 HSPA9 suggests a complex interplay of gene regulation involving KDM3B, ETF1, FAM53C, KLHL3, and DNAJC18, potentially contributing to COVID-19 severity." (PMID 41009536, 2025). "Furthermore, DNAJC18 was found to be involved in virus endoplasmic reticulum membrane penetration and infection, suggesting a potential role in COVID-19 pathogenesis." (PMID 41009536, 2025).
Parkinson disease (1 paper, 2024). A progressive degenerative disorder of the central nervous system characterized by loss of dopamine producing neurons in the substantia nigra and the presence of Lewy bodies in the substantia nigra and locus coeruleus. "Dnajc18 encodes a protein of the DNAJ family, which is highly expressed in the brain and plays a key role in neurodegenerative disorders, such as Parkinson’s Disease, and may also be involved in ubiquitin-dependent ERAD pathway and cellular response to misfolded protein." (PMID 39156629, 2024).
skin cancer (1 paper, 2025). "Six genes (RBM6, DNAJC18, SPIRE2, CPNE1, SEPT2, and ERAP2) presented causal associations with skin cancer." (PMID 41209561, 2025).
bacterial infection (1 paper, 2021). "In addition, DnaJC18, which is part of the Heat shock protein (HSP) family Hsp40, has been found to be upregulated following bacterial infection in catfish, indicating a role in immune system response." (PMID 34745338, 2021).
DNAJC18 also shares sentences with these, for which no sentence is quoted: infection (2 papers); Sepsis (1).